PPIAL4A (peptidylprolyl isomerase A like 4A)
Description:
PPIases accelerate the folding of proteins. It catalyzes the cis-trans isomerization of proline imidic peptide bonds in oligopeptides (By similarity).
Synonyms: COAS-2; COAS2; PPIAL4B; PPIAL4
Tractability: No criterion of Open Targets' tractability assessment is met for any kind of drug.
Gene: Protein-coding gene on chromosome 1 (120,889,771 to 120,890,530, forward strand). Ensembl gene ENSG00000263353.
Subcellular location: Cytoplasm
Gene Ontology:
Molecular function: cyclosporin A binding; peptidyl-prolyl cis-trans isomerase activity
Biological process: protein folding
Cellular component: extracellular exosome; cytoplasm
Genetic constraint (gnomAD): Loss-of-function variants: 6 observed, 6.25 expected, observed/expected ratio (o/e) 0.96, 90% interval 0.52 to 1.74. That is too few expected variants to judge how well the gene tolerates losing a copy. Missense variants: 212 observed, 178.11 expected, observed/expected ratio (o/e) 1.19, 90% interval 1.06 to 1.33. Synonymous variants: 53 observed, 56.97 expected, observed/expected ratio (o/e) 0.93, 90% interval 0.75 to 1.17.
Homologues: Orthologues: zebrafish ppifa (69% identical), zebrafish ppiab (68% identical), Caenorhabditis elegans cyn-3 (65% identical), Caenorhabditis elegans cyn-7 (65% identical), zebrafish ppiaa (65% identical), Caenorhabditis elegans cyn-2 (63% identical), Caenorhabditis elegans cyn-1 (61% identical), Caenorhabditis elegans cyn-9 (49% identical), Drosophila melanogaster Cyp40 (49% identical), Drosophila melanogaster Moca-cyp (46% identical). Paralogues in human: PPIAL4C (98% identical), PPIAL4E (98% identical), PPIAL4F (98% identical), PPIAL4D (97% identical), PPIAL4G (96% identical), PPIAL4H (96% identical), PPIA (86% identical), PPIF (66% identical), PPIE (62% identical), PPID (60% identical), PPIB (56% identical), PPIC (53% identical), and 10 more.
Diseases named in the same sentence as PPIAL4A in open-access papers:
PPIAL4A is named in the same sentence as 2 diseases in open-access papers, as found by Europe PMC text mining. Sharing a sentence is not in itself a finding about the gene and the disease.
PPIAL4A shares sentences with these, for which no sentence is quoted: colon cancers (1 paper); liver cancer (1).